HSPA4 (heat shock protein family A (Hsp70) member 4)
Synonyms: HSPH2; HS24/P52; APG-2; HEL-S-5a; RY; hsp70; hsp70RY
Tractability: PROTAC: ubiquitination databases record sites on it; its protein half-life has been measured.
Gene: Protein-coding gene on chromosome 5 (133,051,946 to 133,106,449, forward strand). Ensembl gene ENSG00000170606.
Subcellular location: Cytoplasm
Subcellular location (Human Protein Atlas): Cytosol; Nucleoplasm
Pathways (Reactome):
Cellular responses to stimuli: Regulation of HSF1-mediated heat shock response
Gene Ontology:
Molecular function: protein binding; adenyl-nucleotide exchange factor activity; ATP binding; ATP hydrolysis activity
Biological process: chaperone-mediated protein complex assembly; protein import into mitochondrial matrix; protein folding; response to unfolded protein
Cellular component: cytosol; extracellular exosome; cytoplasm; organelle
Genetic constraint (gnomAD): Loss-of-function variants: 11 observed, 57.59 expected, observed/expected ratio (o/e) 0.19, 90% interval 0.12 to 0.32. The upper end of that interval is the gene's LOEUF score, 0.32, which puts it in group 1 of 6, group 1 being the genes least tolerant of losing a copy. Missense variants: 563 observed, 656.63 expected, observed/expected ratio (o/e) 0.86, 90% interval 0.8 to 0.92. Synonymous variants: 226 observed, 224.71 expected, observed/expected ratio (o/e) 1.01, 90% interval 0.9 to 1.12.
Homologues: Orthologues: chimpanzee HSPA4 (99% identical), macaque HSPA4 (99% identical), mouse Hspa4 (96% identical), pig HSPA4 (96% identical), rat Hspa4 (96% identical), guinea pig HSPA4 (94% identical), dog HSPA4 (94% identical), rabbit HSPA4 (92% identical), tropical clawed frog hspa4 (81% identical), zebrafish hspa4a (73% identical), zebrafish hspa4b (73% identical), Drosophila melanogaster Hsp110 (44% identical), and 4 more. Paralogues in human: HSPH1 (65% identical), HSPA4L (64% identical), HYOU1 (29% identical), HSPA8 (27% identical), HSPA6 (27% identical), HSPA1L (27% identical), HSPA1A (26% identical), HSPA1B (26% identical), HSPA2 (26% identical), HSPA5 (25% identical), HSPA9 (21% identical), HSPA14 (17% identical), and 1 more.
Diseases named in the same sentence as HSPA4 in open-access papers:
HSPA4 is named in the same sentence as 75 diseases in open-access papers, as found by Europe PMC text mining. Sharing a sentence is not in itself a finding about the gene and the disease. The quoted sentences say what the papers report.
breast carcinoma (19 papers, 2019 to 2025). "In breast cancer patients, pathogenic IgG targeting glycosylated HSPA4 is produced in sentinel lymph nodes by B cells, potentially accelerating lymph node metastasis." (PMID 38305786, 2024). "For example, the now well-understood mechanism underlying the role of anti-HSPA4 IgGs in breast cancer metastasis represents a turning point paradigm." (PMID 33672007, 2021). "For instance, the higher expression of HSPA4 in cancers was associated with metastasis and poor prognosis in breast cancer patients." (PMID 33194682, 2020). "HSPA4 overexpression is associated with the poor prognosis of breast cancer patients." (PMID 34059060, 2021). "Among these autoantibodies, high serum anti-HSPA4 IgG was correlated with high tumor HSPA4 expression and poor prognosis in breast cancer subjects." (PMID 40766308, 2025). "In patients with breast cancer, high tumor expression of HSPA4 and elevated serum levels of anti-HSPA4 IgG were found to be associated with lymph node metastasis and poor prognosis." (PMID 33672007, 2021). "For example, primary tumours induce B cell aggregation in draining lymph nodes, and these B cells selectively promote breast cancer lymph node metastasis through HSPA4‐targeting of IgG." (PMID 32449597, 2020). "Clinically, high HSPA4 expression in breast cancer has been shown to be correlated with increased lymph node metastasis." (PMID 32793473, 2020). "Hsp90AA1, Hsp90AB1, TRAP1, HspA5, HspB1, HspE1, HspD1, HspA1B, HspA8, HspA9, and HspA4 were validated as potential biomarkers for breast cancer tissue." (PMID 31921692, 2019). "Multiple heat shock proteins, including Hsp90AA1, Hsp90AB1, TRAP1, HspA5, HspB1, HspE1, HspD1, HspA1B, HspA8, HspA9, and HspA4, were significantly upregulated in breast cancer tissue." (PMID 31921692, 2019). "Heat shock proteins showed the most significant change of all the upregulated domains, with Hsp90AA1, Hsp90AB1, TRAP1, HspA5, HspB1, HspE1, HspD1, HspA1B, HspA8, HspA9, and HspA4 identified in breast cancer tissue." (PMID 31921692, 2019). "Furthermore, IgG+ plasma cells targeting heat shock protein 4 (HSPA4) in tumor-draining lymph nodes (TDLNs) participate in the formation of the premetastatic niche in breast cancer." (PMID 39744696, 2025). "Indeed, tumor-adapted B cells were capable of secreting pathological antibodies targeting the tumor antigen HSPA4, thereby promoting breast cancer lymph node metastasis." (PMID 38414027, 2024). "HSPA4 is a target when B cells selectively drive lymph node metastasis in breast cancer." (PMID 36292719, 2022). "Another study demonstrated that B cells could enhance the metastatic ability of breast cancer cells by activating the CXCR4/SDF1α axis in tumor cells via secreting HSPA4-targeting immunoglobins." (PMID 36046337, 2022). "B cells selectively promotes breast cancer lymph node metastasis through HSPA4-targeted IgG." (PMID 35223996, 2022). "It has been found extracellular HSP70 could activate ERK1/2, NF-kB, and proinflammatory genes transcription in lung cancer cell, and in breast cancer, tumor-educated B cells could target HSPA4 to promote lymph node metastasis through Src/NF-kB pathway." (PMID 33790969, 2021). "The Mann-Whitney U test showed that five AAbs (HSPA4, PRPF19, ENO1, PRDX6, and MMP14) were significantly higher in the breast cancer group than in the control group." (PMID 40766308, 2025). "We validated these five autoantibodies (HSPA4, ENO1, PRDX6, PRPF19, and MMP14) in an independent cohort of 33 breast cancer patients and 45 healthy controls." (PMID 40766308, 2025). "Anti-HSPA4, anti-PRPF19, anti-ENO1, anti-PRDX6, and anti-MMP14 autoantibodies showed significant increases in breast cancer patients." (PMID 40766308, 2025). "In the verification cohort, IgG autoantibodies against HSPA4, ENO1, PRDX6, PRPF19 and MMP14 were significantly increased in breast cancer patients with areas under the curve (AUCs) of 0.90, 0.89, 0.82, 0.78 and 0.77, respectively." (PMID 40766308, 2025).
breast carcinoma (continued). "Five potential AAb biomarkers (HSPA4, ENO1, PRDX6, PRPF19, MMP14) predictive of breast cancer were identified through verification and validation cohorts." (PMID 40766308, 2025). "At least three genes from this list were involved in the formation of carcinomas, including breast carcinoma (CASP8, HSPA4, BCL2L11), prostate carcinoma (BCL2, CASP8, BCL2L11, ATM), and chronic lymphocytic leukemia (BCL2, CASP8, FAS, BCL2L11, BAK1)." (PMID 37298337, 2023). "The identified PBMC biomarkers (TMSB4X, HSPA4, S100A9, SRSF6, THBS1, CUL4A, and CANX) were significantly upregulated in the breast cancer patients at the metastatic stage compared to both the primary stage and healthy individuals (p < 0.001)." (PMID 32793473, 2020). "All six thermogenes appear to be significantly overexpressed in breast cancer (HSPA1A, HSPA4), gliomas (DNAJB5), ovarian cancers (HSPA4, DNAJB5), pancreatic cancers (HSP90AA1), prostate cancer (HSP90AB1), thymic carcinoma (BAG1, HSP90AA1), and uterine cancers (HSPA4), as compared to normal tissue." (PMID 31814876, 2019). "The role of necroptosis-related genes in breast cancer, such as FASLG, FLT3, HSPA4, IDH2, IPMK, LEF1, and SLC39A7, has not been extensively studied, and these necroptosis-related genes have been confirmed to regulate the biological processes of necroptosis in various types of tumors." (PMID 36675706, 2022).
hepatocellular carcinoma (12 papers, 2011 to 2024). A malignant tumor that arises from hepatocytes. "Evidence suggests that HSPA4 is implicated in the pathogenesis and progression of hepatocellular carcinoma, colorectal cancer, gastric cancer, and head and neck cancer, positioning it as a potential therapeutic target and prognostic biomarker." (PMID 38305786, 2024). "Heat-shock protein family A (Hsp70) member 4 (HSPA4) was involved in the functional stabilization of mutated or aberrantly expressed genes in multiple tumors and had been identified to have a significant correlation with immune regulation and prognosis of hepatocellular carcinoma." (PMID 35754848, 2022). "Bioinformatic studies highlight that high HSPA4 expression is significantly correlated with poor hepatocellular carcinoma prognosis, underscoring its central role in immune modulation." (PMID 38305786, 2024). "HSPA4 responds to acidic pH stress, is involved in the radioadaptive response, and is overexpressed in hepatocellular carcinoma." (PMID 21208456, 2011). "The relationship between HSPA4 and hepatocellular carcinoma has also been scrutinized." (PMID 38305786, 2024). "Univariate and multivariate analyses showed that HSPA4 and HSPA14 could be independent risk factors for the prognosis of hepatocellular carcinoma patients." (PMID 34059060, 2021). "Moreover, the heat shock protein A4 (HSPA4) expression is upregulated in patients affected by hepatitis B virus (HBV)-related hepatocellular carcinoma, in particular in those with earlier recurrence." (PMID 32268515, 2020). "Increased HSPA4 levels were observed in hepatocellular carcinoma, which supports our observation." (PMID 21208456, 2011). "Futhermore, the levels of multiple HSPs including HSPA4 were significantly enhanced in hepatocellular carcinoma (HCC), CRC and head and neck cancer compared with normal tissues." (PMID 35292026, 2022). "Cell experiments have also confirmed that reducing HSPA4 and HSPA14 expressions can inhibit the invasion, metastasis, and proliferation of hepatocellular carcinoma cells." (PMID 34059060, 2021). "For instance, HSPA4 and HSPA14 can be novel therapeutic targets and prognostic biomarkers for hepatocellular carcinoma." (PMID 34059060, 2021). "We made several novel predictions, including that CDK1 and PTPN1 knockdown would be more effective in males with hepatocellular carcinoma, and SMAD3 and HSPA4 knockdown would be more effective in females with head and neck squamous cell carcinoma." (PMID 26755347, 2016). "HSPA4 upregulation is correlated with poor overall survival (OS) in HNSC and hepatocellular carcinoma (HCC)." (PMID 38589927, 2024). "However, the mechanism of HSPA4 and HSPA14 effect on the occurrence and development of hepatocellular carcinoma is unknown and should be studied." (PMID 34059060, 2021). "The scratch spacing significantly decreased in the NC group after 48 h, but there was no significant change in HSPA4 and HSPA14 knockdown groups, indicating that the migration ability of hepatoma cells decreased, similar to the migration and invasion assays." (PMID 34059060, 2021).
gastric cancer (6 papers, 2014 to 2025). A primary or metastatic malignant neoplasm involving the stomach. "In gastric cancer, specific mutations related to HSPA4 are significantly associated with tumorigenesis." (PMID 38305786, 2024). "HSPA9 and HSPA4 were concluded to be associated with the invasion and metastatic activity of gastric cancer." (PMID 25379943, 2014). "We further uncover the molecular mechanism by which HSPA4/ALKBH5/CD58 axis upregulates PDL1 expression in gastric cancer cells and inhibits the cytotoxicity of CD8+ T cells in tumor environment." (PMID 38589927, 2024). "Here we show a different mechanism in gastric cancer: CD58 is negatively posttranscriptionally regulated by HSPA4/ALKBH5 via m6A demethylation." (PMID 38589927, 2024). "Following univariate analysis, RBBP6, DCTPP1, HSPA4, and ALDOA expression levels were significantly associated with poor prognosis in 300 gastric cancer patients." (PMID 25379943, 2014). "RBBP6, DCTPP1, HSPA4, and ALDOA expression in particular were significantly associated with a poor prognosis in the 300 gastric cancer patients." (PMID 25379943, 2014). "HSPA4 is a potential cancer stem cell (CSC) marker for gastric cancer." (PMID 34059060, 2021). "In gastric cancer (GC), histone acetylation upregulated HSPA4, which enhanced ALKBH5 protein stability." (PMID 41562066, 2025).
colorectal cancer (5 papers, 2011 to 2025). A primary or metastatic malignant neoplasm that affects the colon or rectum. "Previous studies reported frameshift mutations of HSPA4 in gastric and colorectal cancers with microsatellite instability." (PMID 34712697, 2021). "The HSPA4 frameshift mutation seems to reduce the survival activity of tumor cells, which may partially explain why patients of gastric and colorectal cancers with microsatellite instability have better prognosis than those with microsatellite stable cancer." (PMID 34712697, 2021). "Evidence suggests that HSPA4, HSP90AB1, DNTM1, RPS27, FTL, NCL, A2M are implicated in the pathogenesis and progression of colorectal cancer, positioning them as potential prognostic biomarkers for the onset of metastasis." (PMID 41319168, 2025). "Intriguingly, the progression of colorectal cancer can be effectively curbed by decreasing HSPA4 expression." (PMID 38305786, 2024). "Intriguingly, previous studies have shown that knocking down HSPA4 results in a G2 phase arrest, suggesting a novel therapeutic avenue for colorectal cancer." (PMID 38305786, 2024). "HSPA4 is not only involved in colorectal cancer (CRC) progression, but also correlates with immune cells in HCC." (PMID 36292719, 2022). "These genes included heat shock 70kDa protein 4 (HSPA4), ubiquitin-conjugating enzyme E2D 2 (UBE2D2), and heat shock 70kDa protein 9 (mortalin/HSPA9), encoding a glucose regulated 75 kilodalton protein previously reported as correlating with poor survival in colorectal cancer." (PMID 21297950, 2011).
glioma (4 papers, 2019 to 2025). A benign or malignant brain and spinal cord tumor that arises from glial cells (astrocytes, oligodendrocytes, ependymal cells). "HSPA4 has been associated with various cancers, including glioma, and a KEGG enrichment analysis revealed that HSPA4 is linked to the PI3K–Akt signaling pathway." (PMID 39599898, 2024). "Elevated HSPA4 expression has been correlated with improved survival in glioma patients." (PMID 40076916, 2025). "Heat shock protein family A (Hsp70) member 4 (HSPA4) was formerly reported to involve inflammation responses and could be used as a biomarker for early lung cancer diagnosis and glioma outcome evaluation." (PMID 33790969, 2021).
lymph node metastasis (4 papers, 2020 to 2022). "In addition, a previous study detected higher mRNA and protein levels of HSPA4 gene in the cancer stem cells with advanced invasion depth, lymph node metastasis or distant metastasis." (PMID 35628491, 2022).
Parkinson disease (4 papers, 2012 to 2025). A progressive degenerative disorder of the central nervous system characterized by loss of dopamine producing neurons in the substantia nigra and the presence of Lewy bodies in the substantia nigra and locus coeruleus. "In a Parkinson’s mouse model, SIRT1-mediated dehydrated to HSPA4 was shown to reduce neuritis." (PMID 40076916, 2025).
head and neck cancer (3 papers, 2020 to 2022). A primary or metastatic malignant neoplasm affecting the head and neck. "Previous analysis illustrated that frequent mutations of HSPH1, HSPD1, HSPA4 and HSP90AA1 were detected in head and neck cancer in head and neck squamous carcinoma." (PMID 34712697, 2021).
head and neck squamous cell carcinoma (3 papers, 2016 to 2024). A squamous cell carcinoma that arises from any of the following anatomic sites: lip and oral cavity, nasal cavity, paranasal sinuses, pharynx, larynx, and salivary glands. "Similarly, in head and neck squamous cell carcinoma, HSPA4 not only emerges as a promising therapeutic target but also might serve as a prognostic biomarker." (PMID 38305786, 2024).
infertile (3 papers, 2015 to 2019). "Among various differentially expressed transcripts, we identified the down-regulation of HSPA4 in the asthenozoospermic group when compared with the normozoospermic infertile group." (PMID 25973848, 2015). "IPA analysis identified that the oxidation of protein pathway was inhibited due to overexpression of HSPA4 (4.08 folds), ALDH1A1 (10.32 folds) and PARK7 (2.69 folds) proteins in the post-antioxidant treatment group of idiopathic infertile men." (PMID 31623114, 2019).
liver cancer (3 papers, 2021 to 2024). An epithelial or non-epithelial malignant neoplasm that arises from the liver. "Previous studies have shown that HSPA4 was overexpressed in liver cancer and was involved in tumor migration, invasion, transformation and recurrence." (PMID 35937592, 2022). "ONCOMINE database datasets showed that the mRNA expression of HSPA4/4L/13/14 was significantly higher in liver cancer tissues." (PMID 34059060, 2021). "Notably, bioinformatics analyses reveal that HSPA4 is significantly overexpressed in gastric, colorectal, and liver cancers." (PMID 38305786, 2024). "HSPA4 expression was positively correlated with the grade of liver cancer in our study." (PMID 35937592, 2022).
lung carcinoma (3 papers, 2020 to 2023). "We found that the polymorphisms of HSPB1 rs2070804 and HSPA4 rs3088225 were significantly associated with lung cancer survival (p=0.015, p=0.049*, respectively)." (PMID 32848724, 2020). "In conclusion, those patients carrying the HSPB1 T allele rs2070804 and the allele A of HSPA4 rs3088225m are carriers of the protective allele in terms of the prognosis of lung cancer." (PMID 32848724, 2020). "What’s more, the genetic polymorphism of HSPA4 rs3088225 (A>G) was significantly associated with the progression free survival (PFS) of lung cancer patients in recessive model [p=0.049, OR=0.44; 95%CI, (0.19–1.00)]." (PMID 32848724, 2020). "In this study, we found that the HSPB1 rs2070804 and HSPA4 rs3088225 polymorphisms are significantly associated with the prognosis in lung cancer patients with the platinum-based chemotherapy treatment." (PMID 32848724, 2020). "In conclusion, we found that the polymorphisms of HSPB1 rs2070804 and HSPA4 rs3088225 were significantly associated with the prognosis in lung cancer patients treated with platinum-based chemotherapy." (PMID 32848724, 2020). "Except for the polymorphisms of HSPB1 rs2070804 and HSPA4 rs3088225, we also found other polymorphisms which are associated with lung cancer prognosis in some specific subgroups." (PMID 32848724, 2020). "In conclusion, the HSPB1 rs2070804 T allele and HSPA4 rs3088225 A allele are the protective allele in the prognosis of lung cancer patients treated with platinum-based chemotherapy." (PMID 32848724, 2020). "Lung cancer patients who carry the HSPB1 rs2070804 T allele or HSPA4 rs3088225 A allele may have a better prognosis compared to the rs2070804 G allele or HSPA4 rs3088225 G allele." (PMID 32848724, 2020). "Association of the HSPB1 rs2070804 polymorphisms and OS, HSPA4 rs3088225 polymorphisms and PFS in lung cancer patients." (PMID 32848724, 2020). "The results of our study suggest that HSPB1 rs2070804 (G>T) and HSPA4 rs3088225 (A>G) may be useful biomarkers for predicting the prognosis of lung cancer patients treated with platinum-based chemotherapy." (PMID 32848724, 2020). "The genotypes of HSPB1 rs2070804 and HSPA4 rs3088225 may be an attractive biomarker used to predict the prognosis of platinum-based chemotherapy lung cancer patients." (PMID 32848724, 2020).
ovarian carcinoma (3 papers, 2019 to 2024). A malignant neoplasm originating from the surface ovarian epithelium. "Furthermore, analysis of data from the Kaplan–Meier plot showed a correlation between higher expression of TCP1, RPL5, HSPA4, and CCT5 and poor prognosis in ovarian cancer." (PMID 39309198, 2024).